OR52E6 (olfactory receptor family 52 subfamily E member 6)
Description:
Odorant receptor.
Synonyms: OR11-58
Tractability: Antibody: UniProt places it where antibodies can reach, with medium confidence; UniProt predicts a signal peptide or a membrane-spanning region; its Gene Ontology location is reachable by antibodies, with medium confidence.
Gene: Protein-coding gene on chromosome 11 (5,840,928 to 5,841,952, reverse strand). Ensembl gene ENSG00000205409.
Subcellular location: Cell membrane
Pathways (Reactome):
Sensory Perception: Expression and translocation of olfactory receptors
Gene Ontology:
Molecular function: olfactory receptor activity; G protein-coupled receptor activity
Biological process: detection of chemical stimulus involved in sensory perception of smell; G protein-coupled receptor signaling pathway; nervous system process
Cellular component: plasma membrane; membrane
Genetic constraint (gnomAD): Loss-of-function variants: 0 observed, 0.0749 expected, observed/expected ratio (o/e) 0, 90% interval 0 to 1.89. That is too few expected variants to judge how well the gene tolerates losing a copy. Missense variants: 418 observed, 390.66 expected, observed/expected ratio (o/e) 1.07, 90% interval 0.99 to 1.16. Synonymous variants: 173 observed, 141.47 expected, observed/expected ratio (o/e) 1.22, 90% interval 1.08 to 1.39.
Homologues: Orthologues: chimpanzee OR52E6 (98% identical), dog OR52E8 (85% identical), mouse Or52e8b (82% identical), rat Or52e8b (82% identical), mouse Or52e8 (81% identical), rat Or52e8 (81% identical), tropical clawed frog or52m1 (43% identical). Paralogues in human: OR52E8 (89% identical), OR52E4 (66% identical), OR52E2 (64% identical), OR52E5 (64% identical), OR52J3 (57% identical), OR52E1 (55% identical), OR52D1 (55% identical), OR52B2 (52% identical), OR52H1 (52% identical), OR52B6 (52% identical), OR52K2 (51% identical), OR52K1 (50% identical), and 39 more.